HMGB1 (high mobility group box 1)
Diseases named in the same sentence as HMGB1 in open-access papers (continued):
Sharing a sentence is not in itself a finding about the gene and the disease.
lung carcinoma (121 papers, 2009 to 2026). "Increased HMGB1 mRNA expression levels were associated with improved lung cancer prognosis, including overall survival (OS), first-progression survival (FP), and post-progression survival (PPS)." (PMID 35923467, 2022). "Cancer‐associated fibroblasts promote metastasis of non‐small cell lung cancer cells by autophagic secretion of HMGB1 via NF‐κB signalling." (PMID 36124714, 2022). "This study showed that higher levels of serum HMGB1 were significantly associated with a higher incidence of postoperative AE-ILD in patients with lung cancer concomitant with ILD, especially in patients who underwent lobectomy." (PMID 33980944, 2021). "In conclusion, higher levels of circulatory HMGB1 are associated with postoperative AE-ILD in patients with lung cancer and ILD." (PMID 33980944, 2021). "For a more rigorous description of HMGB1 as a biomarker associated with monitoring therapy, a longitudinal design collecting serial samples of lung cancer patients was employed." (PMID 34966671, 2021). "Because smoking is a risk factor for lung cancer development and a high proportion of lung cancer patients are heavy smokers or passive smokers, we quantified HMGB1 in these patients and compared the data with healthy smokers." (PMID 34966671, 2021). "This study is the first to show that higher levels of HMGB1 were significantly associated with a higher incidence of postoperative AE-ILD in patients with lung cancer and ILD." (PMID 33980944, 2021). "Many investigations have suggested that HMGB1 gene polymorphisms are correlated with risk factors of lung cancer development." (PMID 32328193, 2020). "In this current study, we estimated the association between SNPs (rs1412125 and rs1360485) in HMGB1 and the susceptibility of lung cancer among 850 cases and 733 controls." (PMID 29617336, 2018). "Results indicated that rs1412125 polymorphism in HMGB1 was associated with the risk of susceptibility to lung cancer, especially with the risk of susceptibility to LAD and SCLC." (PMID 29617336, 2018). "This study aimed to investigate the relationship between rs1412125 and rs1360485 polymorphisms in HMGB1 and the risk and survival of lung cancer." (PMID 29617336, 2018). "HMGB1 expression level was associated with the clinical pathological characteristics of the patients with lung cancer, such as T stage (P = 0.027) and lymph node metastasis of the tumor (P = 0.019), and was closely related to the clinical stage (P = 0.012)." (PMID 29850505, 2018). "HMGB1 is positively associated with the pathological grade and metastasis of liver cancer, and correlated with lung cancer patients’ survival." (PMID 27323831, 2016). "As HMGB1 is a crucial regulator of autophagy and mitophagy 123, autophagy deficiency due to loss of HMGB1 may cause genome instability and inflammation, and promote tumorigenesis of lung cancer." (PMID 28039939, 2017). "We also considered that the mutation of HMGB1 might lead to up-regulation in lung cancer, but the results from TCGA exclude this possibility." (PMID 26840258, 2016). "Thus we conducted this study to evaluate the association between the two SNPs (rs1412125 and rs1360485) in HMGB1 and the susceptibility as well as the survival of lung cancer to provide a new biomarker for the diagnosis, susceptibility and prognosis of lung cancer." (PMID 29617336, 2018). "Finally, not only the pooled analysis but also the stratified analysis was conducted according to the smoking status, genders as well as the pathological types to provide a detailed analysis of the association between the single nucleotide polymorphism in HMGB1 and the lung cancer risk." (PMID 29617336, 2018). "In addition, the potential molecular mechanisms underlying the role of HMGB1 in lung cancer are still unknown." (PMID 29850505, 2018). "However, the underlying mechanisms involving HMGB1 promotion of lung cancer invasion and metastasis still remain unclear and require further elucidation." (PMID 29850505, 2018).
lung carcinoma (continued). "In vitro, transfected BoxA of HMGB1 in lung cancer cell lines reduced cell proliferation, promoting apoptosis, and induced the formation of γH2AX-associated DNA double-strand breaks, and DNA damage response (DDR) related protein." (PMID 40561066, 2025). "Increased expression of MMP-2 in response to HMGB1 has been previously documented in lung cancer cells, and this expression was significantly reduced by NF-κB inhibition." (PMID 40277915, 2025). "In our study, MDRVV induced the release of ATP and HMGB-1, both representative DAMPs, in lung cancer cell lines." (PMID 40867310, 2025). "HMGB1 enhances chemotherapeutic drug resistance in lung cancer cells by promoting autophagy, inhibiting apoptosis, and enhancing cell survival signaling pathways." (PMID 41354099, 2025). "Functional validation experiments were conducted in A549 lung cancer cells to evaluate the effects of HMGB1 knockdown on tumor proliferation and malignancy." (PMID 39717781, 2024). "To further investigate the role of HMGB1, one of the modeling genes of Necroptosis.Sig, in A549 lung cancer cells and animal experiments, we conducted a series of analyses." (PMID 39717781, 2024). "Our results also showed that lipid metabolism plays a significant role in HMGB1 and the immune response to lung cancer." (PMID 39100092, 2024). "Its upregulation suppresses the proliferation and migration of lung cancer cells by targeting HMGB1." (PMID 39759512, 2024). "Inhibiting HMGB1 decreased the expression of distinct immune response-related genes, particularly those regulated by NF-kB signaling, affirming that HMGB1 is a critical mediator in the communication between lung cancer cells and the immune system." (PMID 39100092, 2024). "To measure the impact of endogenous HMGB1 protein on the reporters, we used the natural HMGB1 inhibitor glycyrrhizin to block the function of HMGB1 present in lung cancer cell conditioned media." (PMID 39100092, 2024). "Our previous study showed that CAFs possess a higher level of autophagy than NFs, and autophagic secretion of HMGB1 from CAFs promotes metastasis of lung cancer cells." (PMID 39759028, 2024). "Our previous study demonstrated that high autophagy level of CAFs is pivotal for the autophagic secretion of HMGB1, which promoted the metastasis of lung cancer cells." (PMID 39759028, 2024). "Together, these data are evidence that the relationship between HMGB1 and sirtuin is responsible for the retention of HMGB1 in lung cancer." (PMID 39100092, 2024). "Our in vitro studies illustrated that altering SCD1 activity led to changes in HMGB1 release and concomitant changes in the expression of PD-L1 on the surface of lung cancer cells and innate immune cells." (PMID 39100092, 2024). "The overexpression of miR-325-3p inhibits the proliferation of lung cancer cells by targeting HMGB1." (PMID 39759512, 2024). "This led us to think that part of the effect MUFA has on lung cancer cells involves regulating inflammatory signaling via HMGB1." (PMID 39100092, 2024). "To measure the effect of HMGB1-depleted lung cancer cells on monocytic cells, we incubated our monocyte reporter cells with HMGB1-depleted lung cancer-conditioned media." (PMID 39100092, 2024). "Glucose depletion (GD) induces necrotic cell death in A549 lung carcinoma cells, activating an inflammatory response due to the release of high-mobility group box 1 (HMGB1)." (PMID 37190124, 2023). "Knockdown of HMGB1 in a human lung cancer cell line resulted in increased cell migration and invasion in vitro, as well as increased metastasis in nude mice." (PMID 36831371, 2023). "HMGB1 (high mobility group box B-1) exhibits crucial role in tumor genesis and development, including lung cancer." (PMID 37518006, 2023). "Studies in a mouse lung cancer system provide evidence for another avenue by which HMGB1 drives MDSCs that contribute to metastasis." (PMID 36831371, 2023).
lung carcinoma (continued). "At the same time, we performed a tissues microarray by using patients’ samples and found that the expression level of HMGB1 in lung cancer tissues was considerably higher than that in para-cancerous tissues." (PMID 37932766, 2023). "The circHERC1-miR-142-3p-HMGB1 axis regulates cell migration and invasion in lung cancer cells, but the axis has little effect on cell viability regulation." (PMID 37932766, 2023). "We also conducted EdU, apoptosis and transwell assays to detect the rescue of FOXO1 and HMGB1 knockdown on cell proliferation, apoptosis, migration and invasion in circHERC1 overexpressing lung cancer cells." (PMID 37932766, 2023). "A recent study illustrated that parapoxvirus ovis (ORFV) induced extracellular secretion of HMGB1 and ATP in lung cancer cells." (PMID 36755812, 2022). "HMGB1 is involved in mechanisms that regulate resistance to radiotherapy in pancreatic 13, 14, cervical 8, breast 33, bladder 16, 34, and lung cancers." (PMID 35812184, 2022). "Our current study shows that AMPK is required for HMGB1 phosphorylation in lung cancer cells during cuproptosis, leading to the dissociation of HMGB1 from histones." (PMID 36211458, 2022). "Withdrawn: ‘The LncRNA H19/microRNA‐29b‐3p/HMGB1 signaling axis contributes to the regulation of lung cancer cell growth’, Xiaojun Zhong, Congkai Zhang, Yunlian Diao, Shu Liao, Qingyuan Ling, Zhuoxian Zhang,Jiuhong Zhong, Ping Long." (PMID 33527767, 2022). "Some of these lncRNAs get involved in cancers; for instance, LINC00501 prohibits lung cancer development and metastasis by mediating miR-129-5p/HMGB1 and up-regulated in non-small cell lung cancer (NSCLC) patients." (PMID 36302939, 2022). "We further examined the effects of HMGB1 in regulating lamellipodia and filopodia formation in lung cancer cells by SEM analysis." (PMID 33807275, 2021). "Our results showed that autophagy-dependent HMGB1 secretion by CAFs promoted the metastasis of lung cancer cells." (PMID 34552063, 2021). "Along this line, down-regulation of miR-325 and miR-449a correlated with poor prognosis in lung cancer patients, as these miRNAs negatively targeted HMGB1, resulting in decreased cell migration, invasion, and/or proliferation." (PMID 34073766, 2021). "In summary, we demonstrated that CAFs-secreted HMGB1 promotes lung cancer cell metastasis, in a CAF autophagy-dependent manner, suggesting the potential value of HMGB1 as a novel therapeutic target for lung cancer therapy." (PMID 34552063, 2021). "Our study showed that HMGB1 increased lung cancer cell spreading and polarization, regulated microtubule and actin dynamics to cell protrusions, and promoted lamellipodia and filopodia formation." (PMID 33807275, 2021). "In order to investigate the role of CAF-secreted HMGB1 in CAF mediated metastasis, we added human recombinant HMGB1 or HMGB1 neutralizing antibody to culture medium of lung cancer cells, and IgG was used as an antibody control." (PMID 34552063, 2021). "Collectively, our results show that autophagy-dependent HMGB1 release by CAFs was responsible for stimulating the metastatic potential of lung cancer cells by the activation of the NF-κB signaling pathway, possibly via the interaction of HMGB1 with TLR4." (PMID 34552063, 2021). "High mobility group box 1 (HMGB1) secreted by CAFs mediated CAFs’ effect on lung cancer cell invasion, demonstrated by using recombinant HMGB1, HMGB1 neutralizing antibody, and HMGB1 inhibitor glycyrrhizin (GA)." (PMID 34552063, 2021). "In this study, we investigated the relevance of soluble HMGB1 for the prediction and monitoring of therapy response as well as the estimation of prognosis in advanced lung cancer." (PMID 33672622, 2021). "For instance, miR-449a was verified to suppress the proliferation and metastasis of tumours in lung cancer by targeting an HMGB1-mediated NF-κB signalling pathway." (PMID 34539874, 2021).
lung carcinoma (continued). "PD-L1/PD-1 upregulation mediated by autocrine and paracrine activation of the HMGB1/RAGE/NF-κB signaling is a key response of lung cancer cells and their TAMs to stress, which can be induced by Nano-DOX." (PMID 34488792, 2021). "High mobility group box 1 (HMGB1) has been shown to promote autophagy protection in response to docetaxel therapy in lung cancer through the activation of the ERK signalling pathway." (PMID 34948097, 2021). "This study aimed to elucidate the association between serum levels of HMGB1 and the development of postoperative AE-ILD in patients with lung cancer concomitant with ILD." (PMID 33980944, 2021). "Further study demonstrated that HMGB1 facilitated lung cancer cell invasion by activating the NFκB pathway." (PMID 34552063, 2021). "Our previous study has compared the gene expression profile between CAFs and NFs derived from lung cancer tissues by RNA sequencing, and we found that HMGB1 is one of the highly expressed genes in CAFs." (PMID 34552063, 2021). "As expected, significant repression of CAFs’ effect on lung cancer cell migration and invasion was observed following inhibition of HMGB1." (PMID 34552063, 2021). "To achieve this, we evaluated the relevance of soluble HMGB1 in serum samples for the prediction and monitoring of therapy response as well as the estimation of prognosis in patients with advanced lung cancer." (PMID 33672622, 2021). "The regulation of mitochondrial membrane tension, dynamics, polarization, fission process, and cytoskeletal rearrangements in lung cancer cells by HMGB1 was analyzed using confocal microscopy." (PMID 33807275, 2021). "Taken together, these findings demonstrated that CAFs facilitated lung cancer cell metastasis by secreting HMGB1." (PMID 34552063, 2021). "A previous study indicated that HMGB1 plays a critical role in tumor development, epithelial–mesenchymal transition, and the prognosis of lung cancer." (PMID 33807275, 2021). "A previous study revealed that NETs were produced by neutrophils in a toll-like receptor 4 (TLR4) and high-mobility group box 1 (HMGB1)-dependent manner in lung cancer cells." (PMID 34476216, 2021). "To investigate if gemcitabine induces CRT and HMGB1 exposure, we treated lung cancer cells with gemcitabine (5, 10, 50, 100, or 500 nM) in vitro." (PMID 32161598, 2020). "In lung cancer microenvironment, binding of HMGB1 to RAGE activates immune cells; on the other hand, it can also contribute to cancer cell proliferation and invasion." (PMID 32456685, 2020). "In conclusion, our study suggested that REV3L rs462779 was significantly associated with overall survival and lymph node metastasis in lung cancer patients with platinum-based chemotherapy, and HMGB1 rs1045411 was related to overall survival and T stage." (PMID 32489453, 2020). "In our study, we observed that low-dose gemcitabine treatment enhanced the immunogenicity of lung cancer by increasing the exposure of calreticulin, high mobility group box 1, and upregulating expression of NKG2D ligands." (PMID 32161598, 2020). "Murine and human lung cancer cells treated with gemcitabine caused CRT expression from membranes and HMGB1 exposure from nuclei in vitro." (PMID 32161598, 2020). "In published papers, GL was reported to downregulate HMGB1 expression in lung cancer cells and in rat brain tissue after acute subarachnoid hemorrhage." (PMID 31929852, 2019). "In the present study, our aim was to characterize the association between the expression of HMGB1 and the clinicopathological and prognostic factors of NSCLC and to investigate how HMGB1 promotes lung cancer invasion and metastasis." (PMID 29850505, 2018). "Several studies have reported a significant role of high mobility group box protein 1 (HMGB1) in lung cancer." (PMID 29850505, 2018). "We also showed that HMGB1 promoted lung cancer invasion and metastasis by upregulating the expression and activity of MMP-2 in an NF-κB-dependent manner." (PMID 29850505, 2018).
lung carcinoma (continued). "Overall, the results showed that the high expression of HMGB1 was closely related to the poor prognoses of patients with lung cancer." (PMID 29850505, 2018). "The clinical analyses showed a significantly higher expression of HMGB1 in the lung cancer tissues than in the adjacent normal tissues." (PMID 29850505, 2018). "HMGB1 was reported to promote the migration and invasion of lung cancer cells and facilitate lung cancer metastasis." (PMID 29568761, 2018). "They examined four HMGB1 SNPs (rs2249825, rs1360485, rs1045411 and rs1412125) in 190 lung cancer cases and 187 healthy controls." (PMID 29617336, 2018). "The increased invasiveness was significantly different, suggesting that treatment with HMGB1 increases the invasive ability of lung cancer cells." (PMID 29850505, 2018). "HMGB1 is overexpressed in many cancers, and plasma HMGB1 levels are elevated in patients with lung cancer." (PMID 29853785, 2018). "And high level of HMGB1 promoted the migration and invasion of lung cancer cells, which was suppressed by glycyrrhizin." (PMID 29568761, 2018). "The direct role of HMGB1 in anticancer effect of glycyrrhizin on lung cancer progression needs further study." (PMID 29568761, 2018). "HMGB1 secretion leads to a higher growth and invasive potential of lung cancer cell lines dependent of RAGE and TLR4 signaling." (PMID 29472602, 2018). "We therefore investigated the clinicopathological and prognostic significance as well as the potential role of HMGB1 in the development and progression of lung cancer." (PMID 29850505, 2018). "In order to understand the role of HMGB1 in lung cancer cells, HMGB1 was overexpressed by lentiviral transduction or silenced by siRNA in lung adenocarcinoma A549 cells." (PMID 28727734, 2017). "Overall, these data strongly suggest that miR-200c transfection significantly downregulated HMGB1 and suppressed HMGB1-regulated lung cancer EMT and progression." (PMID 28727734, 2017). "HMGB1 affects tumour growth, metastasis, and prognosis through multiple signalling pathways in cancers, including lung cancer, osteosarcoma, gastric cancer, cervical cancer, and HCC." (PMID 29246127, 2017). "The results showed that we successfully overexpressed or silenced HMGB1 expression in lung cancer cells." (PMID 28727734, 2017). "HMGB1-mediated autophagy, resulting in aggravating chemoresistance, has been demonstrated in cancers, including osteosarcoma, lung cancer, leukaemia, and gastric cancer." (PMID 29246127, 2017). "In order to characterise the expression of HMGB1 and EMT-associated proteins in lung cancer, immunohistochemistry was performed in human NSCLC tissue." (PMID 28727734, 2017). "Taken together with previous reports, our findings suggest that HMGB1 is a key regulator of EMT in lung cancer." (PMID 28727734, 2017). "HMGB1 and CpG oligonucleotides synergistically enhanced the proliferation and invasive potential of human lung cancer cells via the interaction with RAGE." (PMID 27026438, 2016). "Serum HMGB1 levels in patients with lung cancer were significantly higher than those in COPD patients and healthy patients." (PMID 26798204, 2015). "They first demonstrated that serum HMGB1 levels were significantly augmented both in patients with lung cancer and in patients with COPD." (PMID 26798204, 2015). "Recently, the impact of cancer-associated fibroblasts on the expression and localization of HMGB1 in lung cancer cells has been demonstrated to operate via the release of diffusible factors from fibroblasts." (PMID 25512109, 2014). "We found that knockdown of HMGB1 in human lung cancer A549 cells significantly increased cell β-actin polymerization, cell skeleton formation, cancer cell migration and invasion in vitro, as well as metastasis in vivo." (PMID 25277185, 2014). "This evidence indicates that HMGB1 operates as an oncogene in lung cancer." (PMID 41194272, 2025).